INS (insulin)
Diseases named in the same sentence as INS in open-access papers (continued):
Sharing a sentence is not in itself a finding about the gene and the disease.
diabetes (continued). "An association between integrins and the onset of diabetes has been noted, with integrins even participating in the regulation of insulin activity in muscle during the early stages of insulin resistance." (PMID 40309438, 2025). "Diabetes is characterized by hyperglycemia caused by insulin insufficiency due to damage to pancreatic beta cells in type 1 diabetes (T1D) or impaired insulin sensitivity and resistance in type 2 diabetes (T2D), or a combination of both mechanisms over time." (PMID 41301913, 2025). "Infections, and in some cases, the treatments applied to them, can alter the balance of glucose in the body, affecting insulin production and effectiveness and increasing the risk of developing diabetes." (PMID 40284028, 2025). "Future research should prioritize randomized controlled trials to validate these findings, with particular attention to high-risk subgroups such as insulin-dependent patients or those with long diabetes duration." (PMID 40568192, 2025). "Diabetes, although primarily a disorder of insulin metabolism caused by elevated blood glucose levels, has significant systemic impacts and can lead to a range of complications, including ocular diseases." (PMID 40422047, 2025). "Following these findings, it became evident that the diabetes phenotype associated with mitochondrial dysfunction is variable, ranging from insulin-dependent to non–insulin–dependent." (PMID 41323015, 2025). "These lipidomic markers, individually or in combination, were linked to diabetes and measures of glucose and insulin homeostasis, above and over clinical covariates." (PMID 41286497, 2025). "Pancreoprivic diabetes inherently resulting from TP represents the most severe form of diabetes due to complete insulin and glucagon deficiency and consecutively is often associated with severe metabolic lability and frequent hypoglycemia." (PMID 40720532, 2025). "This is especially true for patients with diabetes treated with insulin, who show higher rates of MACE, all-cause mortality and target lesion revascularization." (PMID 40687396, 2025). "Diabetes mellitus was diagnosed 3 years earlier after polyuria, polydipsia, and weight loss; however, glycemic control remained suboptimal despite multiple insulin regimens." (PMID 40979821, 2025). "Diabetes mellitus, a chronic disease caused by insufficient insulin production or ineffective insulin utilisation, has become a severe global public health issue." (PMID 41002328, 2025). "Diabetes pathogenesis can be linked to inflammation through IL-6 elevation, which also contributes to impaired insulin signaling and hepatic glucose output." (PMID 41011232, 2025). "Diabetes mellitus (DM) is a metabolic disorder associated with impaired signaling & resistance of insulin, and β‐cell dysfunction, increased oxidative stress, sub‐clinical inflammation, abnormal glucose and lipid metabolism." (PMID 40585503, 2025). "Type 2 diabetes mellitus (T2D) represents a metabolic imbalance of insulin needs and sensitivity caused by multiple etiological factors resulting in clinical features, such as hyperglycemia, insulin resistance and insufficient insulin secretion." (PMID 40962878, 2025). "T1D is a clinical form of diabetes mellitus characterized by an absolute deficiency of insulin due to the destruction of pancreatic β-cells." (PMID 40238817, 2025). "In line with our findings that the PRS of diabetes-related traits are significantly associated with BIs, the “leptin-insulin signaling pathway overlap” was also a top-ranked pathway." (PMID 40650217, 2025). "A s individuals age, the risk of developing diabetes increases due to age-related changes in pancreatic β cells, including reduced glucose sensitivity and insulin secretion." (PMID 40552178, 2025). "This lack of association between galactin-3 and insulin resistance in the current study appears to be at variance with previous studies that associated galectin-3 with insulin signaling and incidence and prevalence of diabetes." (PMID 40802820, 2025).
diabetes (continued). "In the diagnostics of diabetes, specific targeting ofdrugs (e.g.,liraglutide) to insulin-deficient β-cells with their simultaneousnoninvasive imaging is currently needed." (PMID 40665745, 2025). "This can be explained by multiple factors related to diabetes management as the emphasis on diet and glycemic targets, the focus on achievement of ideal body mass index (BMI), insulin-related weight gain, and associated body image dissatisfaction." (PMID 40163174, 2025). "Overall, Type I dInr adults in particular have three features associated with human pre-diabetes: hyperinsulinemia, mechanisms to increase insulin peptide bioavailability, and impaired insulin receptor sensitivity." (PMID 40523036, 2025). "A different finding was found by a study by Lemieux, which showed that a 6-month vitamin D supplementation in individuals at high risk of diabetes or with newly diagnosed T2DM significantly increased peripheral insulin sensitivity." (PMID 40806075, 2025). "T2DM is the dominant type of diabetes mellitus characterized by metabolic disorders, insulin resistance, and deficiency of insulin secretion." (PMID 40878918, 2025). "Variants in the CAPN10 gene (rs3792267, rs2975760, and rs5030952) have been associated with impaired insulin secretion and increased type 2 diabetes mellitus risk across multiple ethnic groups, including Asians." (PMID 40944253, 2025). "The dysfunction of β-cells, typified by a decrease in β-cell mass and impaired insulin secretion, is intimately linked to the pathogenesis and progression of diabetes mellitus." (PMID 41008194, 2025). "Primary consequences of diabetes that drive DSPN include loss of insulin signaling arising from insulinopenia or insulin resistance and chronic hyperglycemia." (PMID 40806522, 2025). "Increased CTSS expression in the serum of elderly people correlate with diminished insulin responsiveness and a heightened risk of type 2 diabetes mellitus." (PMID 39964999, 2025). "It has been reported that apelin secretion by adipose tissue is modulated by nutritional status, such as hunger and satiety, and its release increases via insulin stimulation, which suggests a direct association with diabetes." (PMID 40195898, 2025). "Diabetes is characterized by hyperglycemia resulting from an absolute or relative deficiency in insulin production or action." (PMID 40510890, 2025). "Heightened AKT activity improves insulin sensitivity and protects against obesity and diabetes associated with metabolic syndrome." (PMID 40166461, 2025). "Ninety to ninety-five percent of cases of diabetic mellitus “T2D” are caused by impaired insulin sensitivity in the target tissues, which causes a disruption in insulin secretion." (PMID 40541974, 2025). "Diabetes is a metabolic disorder diseases caused by insufficient insulin secretion or impaired insulin action (Weir, Gaglia & Bonner-Weir, 2020)." (PMID 40386230, 2025). "When the function of islet β cells is damaged and the insulin secretion becomes absolutely or relatively deficient, the blood glucose levels rise, eventually resulting in diabetes." (PMID 40508108, 2025). "Diabetes is a complex, chronic, and progressively worsening metabolic disorder, caused by either an absolute or relative deficiency of insulin or by reduced insulin activity." (PMID 39941054, 2025). "Excess visceral fat promotes lipotoxicity, oxidative stress, and systemic inflammation that impair insulin signaling pathways, thereby increasing the risk of type 2 diabetes mellitus (T2DM) and cardiovascular disease (CVD)." (PMID 40895654, 2025). "The primary causes of hyperglycemia in diabetes include reduced insulin production (type I diabetes) or inefficient insulin utilization (type II diabetes)." (PMID 40149100, 2025). "The age-related increase in susceptibility to prediabetes and diabetes is attributed to declining insulin secretion, compromised pancreatic function, and heightened insulin resistance." (PMID 40747186, 2025).
diabetes (continued). "Here, we show that VH125SD.NOD mice with T cell loss of BCL6 still produce peripheral anti-insulin B cells yet are protected against diabetes (relative to Bcl6-sufficient controls)." (PMID 40909612, 2025). "Diabetes mellitus is an endocrine disorder caused either by insufficient insulin production by the pancreas or by the body’s inability to respond effectively to insulin." (PMID 40292569, 2025). "Restricted food intake or dehydration (i.e. perioperative fasting) and increased insulin requirements due to acute illness or surgery can also predispose people with diabetes to developing DKA." (PMID 40651878, 2025). "This diverges from findings in the general population, where diabetes is a well-established frailty risk factor via insulin resistance, oxidative stress, and microvascular dysfunction." (PMID 40514576, 2025). "Our analysis shows that increased engagement with the isCGM system for people with diabetes has a greater association with glycaemic control than does more‐frequent insulin bolus dosing." (PMID 41039947, 2025). "Treatment-induced neuropathy of diabetes (TIND) is an iatrogenic complication associated with insulin therapy, particularly in patients with type 1 diabetes mellitus (T1DM)." (PMID 41347129, 2025). "This form encompasses individuals who generally have relative (rather than absolute) insulin deficiency and have insulin resistance (i.e., decreased biological responses to insulin)." (PMID 41357171, 2025). "Monogenic diabetes, although representing a minor proportion of overall diabetes cases, is primarily attributed to mutations in individual genes vital for insulin production or its action." (PMID 40862129, 2025). "Omentin-1: Omentin-1, an adipokine associated with insulin sensitization, is found to increase with age and is linked to metabolic disturbances like obesity and diabetes." (PMID 40852589, 2025). "As individuals age, various changes in body composition, insulin sensitivity, and glucose metabolism occur, which can elevate the risk of developing diabetes." (PMID 41049430, 2025). "Self-monitoring of blood glucose and taking insulin injections have previously been found to cause psychosocial problems in people with diabetes." (PMID 40275867, 2025). "While metformin has been associated with reduced cancer risk, newer diabetes medications, such as insulin analogs and sulfonylureas, have been linked to a potentially increased cancer risk." (PMID 40998759, 2025). "A total of 359 patients with endogenous insulin-deficient diabetes who met the inclusion criteria were enrolled in this study." (PMID 41586239, 2025). "Research using a genetically engineered mouse model has shown that the Glu23 variant, when combined with a high-fat diet and obesity, hinders glucose-induced insulin secretion, and increases the risk of diabetes." (PMID 40650956, 2025). "Both GPR40 and GPR119 agonists are crucial for diabetes treatment by regulating insulin secretion, reducing the risk of hypoglycemia, and providing new drug targets." (PMID 41427055, 2025). "Low plasma ghrelin levels are associated with elevated fasting insulin levels and insulin resistance, which can contribute to the development of type 2 diabetes mellitus." (PMID 41155523, 2025). "In this study, two patients were positive for diabetes autoantibodies, one younger than 2 years of age and another with a family history of diabetes, for whom the INS variant was identified through genetic investigation." (PMID 40303944, 2025). "Studies have highlighted that participants following the DASH diet experience improved insulin sensitivity and reduced metabolic risk factors linked to changes in DNA methylation patterns associated with obesity and diabetes." (PMID 40917096, 2025). "These lipids were associated with diabetes risk, potentially through mediating the protective effects of PA on insulin sensitivity." (PMID 41286497, 2025).
diabetes (continued). "In another cat, the diet was not changed because of the risk of dysregulation of the cat's diabetes mellitus that was well controlled with diet and insulin." (PMID 40110650, 2025). "Insulin is a mainstay treatment for diabetes, but its use is associated with weight gain and hypoglycaemia." (PMID 40036884, 2025). "Intracellular serotonin regulates insulin secretion from pancreatic β cells through serotonylation of GTPases (Rab3a and Rab27a), and mice selectively deficient in serotonin develop diabetes." (PMID 39926388, 2025). "Fiber intake is associated with lower levels of the inflammatory serum marker C-reactive protein (CRP) and improved insulin sensitivity, which in turn can mitigate the chronic inflammatory state associated with diabetes and depression." (PMID 40658313, 2025). "Healthcare providers should integrate discussions of sexual health into routine diabetes counseling and proactively address the risk of post-coital hypoglycemia, particularly for insulin-treated and younger patients." (PMID 41030722, 2025). "Overall, Type I dInr adults have three features associated with human diabetes: hyperinsulinemia, mechanisms to increase insulin peptide bioavailability, and impaired insulin receptor sensitivity." (PMID 40093182, 2025). "This retrospective analysis of two independent cohorts (MIMIC and TJHFIT) in patients with comorbid chronic heart failure and type 2 diabetes mellitus (CHF‐T2DM) investigates the association between in‐hospital insulin therapy and mortality." (PMID 41320960, 2025). "The risk of diabetes-specific eating disorders was identified in six patients (30%) using insulin infusion pumps and in nine patients (20.4%) using multiple daily injections (p = 0.403)." (PMID 41010976, 2025). "The majority of patients with INS variants are diagnosed with diabetes younger than 6 months of age." (PMID 39717432, 2025). "Logistic and linear regression was used to evaluate the associations of PA-related lipids with incident diabetes/prediabetes and glucose/insulin metrics." (PMID 41286497, 2025). "Short-term LCD intervention improved GV in insulin-deficient diabetes, especially in patients with more significant β-cell dysfunction, with blood ketones negatively correlated with blood glucose and GV." (PMID 41586239, 2025). "Recently, large population-based observational studies in Europe on patients with type 1 diabetes mellitus showed a decreased risk of DKA with insulin pump use." (PMID 41146752, 2025). "Patients with insulin use and diabetes duration (average 5.3 years) had an increased risk of tendinopathy." (PMID 40616074, 2025). "Insulin pump therapy is associated with improved and sustained glycemic control in patients with type 1 diabetes mellitus." (PMID 41146752, 2025). "The causal effect of exogenous insulin use (ukb-b-7350) on diabetes and smoking was obtained from univariate MR Analysis, and the direct effect of diabetes and smoking on OA was obtained from multivariate MR Analysis." (PMID 41398760, 2025). "In contrast, for patients with SPIDDM who have already been diagnosed with diabetes, anti-islet autoantibodies are used as predictive markers for progression to an insulin-deficient state." (PMID 40650275, 2025). "Low baseline levels and large changes in β-cell function and insulin sensitivity indices increased the risk of diabetes." (PMID 40361840, 2025). "Diabetes mellitus encompasses a group of metabolic disorders characterized by hyperglycemia caused by insulin production deficiency and/or insulin resistance." (PMID 40667952, 2025). "GABA interventions in diabetic conditions are associated with significant improvements in glucose and insulin homeostasis, enhancements in lipid profiles, and reductions in organ dysfunctions related to diabetes." (PMID 40149935, 2025).
diabetes (continued). "The WFS1 mutant disrupts the receptor splice site and affects the pattern of mRNA splicing, which leads to β‐cell apoptosis and promotes β‐cell dedifferentiation and loss of normal insulin secretion, leading to diabetes." (PMID 40641032, 2025). "The absence of ApoER2 in bone-marrow-derived macrophages accelerates obesity and diabetes onset, while its deficiency in other tissues leads to hyperglycemia and inflammation due to defective insulin secretion." (PMID 40005876, 2025). "The concurrent diagnosis of type 4 RTA complicated glucose and electrolyte management, as insulin is both therapeutic for hyperkalemia and a risk for hypoglycemia in brittle diabetes." (PMID 41146800, 2025). "Heart failure is one of the most common complications of diabetes mellitus, while diabetes mellitus is also an independent risk factor for heart failure (including coronary artery disease, insulin use and elevated serum creatinine in diabetic patients)." (PMID 40507126, 2025). "This leads to impaired insulin secretion and the development of hyperglycemia, a hallmark of diabetes." (PMID 40548186, 2025). "Additional studies have shown that miR-144-3p impacts insulin secretion and sensitivity, reinforcing its role in the development of diabetes and associated complications." (PMID 40626241, 2025). "Poor glycemic control was common and significantly associated with longer diabetes duration and insulin-based treatment regimens." (PMID 40385776, 2025). "At the 3-month follow-up (primary end point), higher age, being separated or divorced, and having a diabetes diagnosis (as well as taking antidiabetics and insulin) were significantly associated with a higher probability of attrition." (PMID 39928931, 2025). "The proposedpathogenic mechanism underlying MODY8 involves the abnormal aggregation of mutantproteins, which increases ER stress in acinar cells, subsequently leading to theonset of diabetes associated with impaired insulin secretion." (PMID 40840513, 2025). "Diabetes mellitus (DM) is a group of chronic metabolic diseases caused by impaired insulin secretion, insulin resistance or both, with hyperglycemia as the main feature." (PMID 41322694, 2025). "The main cause of diabetes is either a defect in insulin production by the β-cells of the pancreas (type 1) or impaired insulin signaling/action (type 2)." (PMID 41002973, 2025). "Type 1 diabetes mellitus (T1D) is a chronic disease caused by progressive autoimmune destruction of insulin-producing pancreatic β cells, leading to lifelong dependence on exogenous insulin." (PMID 39870583, 2025). "Diabetes mellitus (DM) is a chronic metabolic disorder characterized by hyperglycemia, caused by an absolute or relative deficiency of insulin and impaired glucose utilization." (PMID 40951432, 2025). "Rorsman and Ashcroft elegantly showed that in order to mitigate severe pancreatic damage associated with different types of diabetes, it is essential to review the β-cell electrophysiology and insulin exocytosis." (PMID 40014914, 2025). "After further adjustment of insulin measurements, the associations of serum propionate with diabetes remained significant (P < 0.05, FDR < 0.05)." (PMID 40078932, 2025). "Insulin resistance (IR), a hallmark feature of diabetes and obesity, is characterized by diminished responsiveness of insulin-sensitive tissues to insulin stimulation." (PMID 41419984, 2025). "Maintaining target blood glucose levels in diabetes is challenging, as bolus insulin injections increase hypoglycemia risk." (PMID 41049970, 2025). "Recessive INS variations can cause neonatal diabetes, whereas the dominant INS can cause both neonatal diabetes and MODY phenotypes." (PMID 40303944, 2025). "Diabetes-related weight gain, particularly associated with specific diabetes treatments such as sulfonylureas, thiazolidinediones, or insulin, can exacerbate OSA by increasing upper airway tissue mass and reducing airway diameter." (PMID 41155523, 2025).